HDAC6 (histone deacetylase 6)
Description:
Deacetylates a wide range of non-histone substrates. Plays a central role in microtubule-dependent cell motility by mediating deacetylation of tubulin. Required for cilia disassembly via deacetylation of alpha-tubulin. Alpha-tubulin deacetylation results in destabilization of dynamic microtubules (By similarity). Promotes deacetylation of CTTN, leading to actin polymerization, promotion of autophagosome-lysosome fusion and completion of autophagy. Deacetylates SQSTM1. Deacetylates peroxiredoxins PRDX1 and PRDX2, decreasing their reducing activity. Deacetylates antiviral protein RIGI in the presence of viral mRNAs which is required for viral RNA detection by RIGI (By similarity). Deacetylates RHOT1/MIRO1 which blocks mitochondrial transport and mediates axon growth inhibition (By similarity). Deacetylates transcription factor SP1 which leads to increased expression of ENG, positively regulating angiogenesis. Deacetylates KHDRBS1/SAM68 which regulates alternative splicing by inhibiting the inclusion of CD44 alternate exons. Deacetylates PRDM16 (By similarity). Acts as a valine sensor by binding to valine through the primate-specific SE14 repeat region. In valine deprivation conditions, translocates from the cytoplasm to the nucleus where it deacetylates TET2 which promotes TET2-dependent DNA demethylation, leading to DNA damage. Promotes odontoblast differentiation following IPO7-mediated nuclear import and subsequent repression of RUNX2 expression (By similarity). In addition to its protein deacetylase activity, plays a key role in the degradation of misfolded proteins: when misfolded proteins are too abundant to be degraded by the chaperone refolding system and the ubiquitin-proteasome, mediates the transport of misfolded proteins to a cytoplasmic juxtanuclear structure called aggresome. Probably acts as an adapter that recognizes polyubiquitinated misfolded proteins and targets them to the aggresome, facilitating their clearance by autophagy. Involved in the MTA1-mediated epigenetic regulation of ESR1 expression in breast cancer. (Microbial infection) Deacetylates the SARS-CoV-2 N protein which promotes association of the viral N protein with human G3BP1, leading to disruption of cellular stress granule formation and facilitating viral replication.
Synonyms: KIAA0901; JM21; HD6; FLJ16239; PPP1R90; KDAC6; CPBHM
Tractability: Small molecule: an approved drug acts on it; a structure with a bound ligand is known; a high-quality ligand is known; it belongs to a druggable protein family. PROTAC: it is named in the literature on targeted protein degradation; UniProt records ubiquitination sites on it; ubiquitination databases record sites on it; its protein half-life has been measured; a small molecule that binds it is known. Other modalities: an approved drug acts on it.
Target class: HDAC class IIb; Epigenetic regulator; Eraser; Histone deacetylase
Chemical probes: ACY-738 (high quality), AVS-100 (high quality), MPI_5a, MPT0G211, NEXTURASTAT A (high quality), PD081043, PD081151, PD081155, PD081195, PD081386, PD081623, PD081670, PD081691, PD082349, PD082450, PD082506, PD083003, PD083048, PD083526, PD083584, and 44 more
Gene: Protein-coding gene on chromosome X (48,801,377 to 48,824,986, forward strand). Ensembl gene ENSG00000094631.
Subcellular location: Cytoplasm; Cytoplasm, cytoskeleton; Nucleus; Perikaryon; Cell projection, dendrite; Cell projection, axon; Cell projection, cilium; Cytoplasm, cytoskeleton, microtubule organizing center, centrosome; Cytoplasm, cytoskeleton, cilium basal body
Subcellular location (Human Protein Atlas): Basal body; Centrosome; Cytosol; Nucleoplasm
Pathways (Reactome):
Autophagy: Aggrephagy; Chaperone Mediated Autophagy; Late endosomal microautophagy
Gene expression (Transcription): Notch-HLH transcription pathway; RUNX2 regulates osteoblast differentiation; Transcriptional regulation by RUNX2
Disease: Constitutive Signaling by NOTCH1 HD+PEST Domain Mutants; Constitutive Signaling by NOTCH1 PEST Domain Mutants
Cellular responses to stimuli: HSF1 activation
Developmental Biology: Differentiation of naive CD4+ T cells to T helper 2 cells (Th2 cells)
Organelle biogenesis and maintenance: Cargo trafficking to the periciliary membrane
Signal Transduction: NOTCH1 Intracellular Domain Regulates Transcription
Gene Ontology:
Molecular function: acetylspermidine deacetylase activity; alpha-tubulin binding; ATPase inhibitor activity; beta-catenin binding; dynein complex binding; enzyme binding; histone deacetylase activity; histone deacetylase binding; Hsp90 protein binding; microtubule binding; misfolded protein binding; peroxidase inhibitor activity; polyubiquitin modification-dependent protein binding; protein binding; protein lysine deacetylase activity; RNA polymerase II cis-regulatory region sequence-specific DNA binding; tau protein binding; transcription corepressor binding; tubulin deacetylase activity; ubiquitin protein ligase activity; ubiquitin protein ligase binding; deacetylase activity; beta-tubulin binding; ubiquitin binding; zinc ion binding
Biological process: aggresome assembly; axonal transport of mitochondrion; cellular response to hydrogen peroxide; cellular response to topologically incorrect protein; cilium disassembly; epidermal growth factor receptor signaling pathway; intracellular protein transport; lysosome localization; negative regulation of aggrephagy; negative regulation of gene expression, epigenetic; negative regulation of hydrogen peroxide metabolic process; negative regulation of protein-containing complex assembly; negative regulation of protein-containing complex disassembly; negative regulation of proteolysis; polyubiquitinated misfolded protein transport; positive regulation of epithelial cell migration; positive regulation of intracellular estrogen receptor signaling pathway; positive regulation of protein oligomerization; protein deacetylation; protein quality control for misfolded or incompletely synthesized proteins; regulation of macroautophagy; regulation of microtubule-based movement; regulation of protein stability; response to misfolded protein; tubulin deacetylation; and 16 more
Cellular component: aggresome; caveola; cell leading edge; centrosome; ciliary basal body; cytoplasm; cytosol; histone deacetylase complex; inclusion body; microtubule; microtubule associated complex; nucleus; perinuclear region of cytoplasm; axon; dendrite; multivesicular body; perikaryon; axon cytoplasm; cell body; cilium; cytoplasmic ubiquitin ligase complex; cytoskeleton; microtubule cytoskeleton; neuron projection; plasma membrane bounded cell projection; and 1 more
Homologues: Orthologues: macaque HDAC6 (99% identical), rabbit HDAC6 (80% identical), dog HDAC6 (80% identical), guinea pig HDAC6 (77% identical), pig HDAC6 (77% identical), rat Hdac6 (75% identical), mouse Hdac6 (74% identical), zebrafish hdac6 (44% identical), Drosophila melanogaster HDAC6 (36% identical), Caenorhabditis elegans hda-6 (30% identical), tropical clawed frog hdac6 (29% identical). Paralogues in human: HDAC4 (23% identical), HDAC10 (22% identical), HDAC7 (21% identical), HDAC5 (20% identical), HDAC9 (20% identical), HDAC1 (9% identical), HDAC2 (9% identical), HDAC8 (8% identical), HDAC3 (7% identical), HDAC11 (6% identical).
Diseases named in the same sentence as HDAC6 in open-access papers:
HDAC6 is named in the same sentence as 372 diseases in open-access papers, as found by Europe PMC text mining. Sharing a sentence is not in itself a finding about the gene and the disease. The quoted sentences say what the papers report.
breast cancer (107 papers, 2008 to 2025). A primary or metastatic malignant neoplasm involving the breast. "In breast cancer models, HDAC6 is implicated in promoting metastatic dissemination and enhancing the motility of cancer cells." (PMID 41300448, 2025). "A novel truncated mRNA transcript for HDAC6, Hhdac6p114 variant, which was described in lung and breast cancer cells lines, is devoid of the HDAC6 nuclear export signal." (PMID 39941046, 2025). "Simultaneously, DEHP has been reported to not only mediate drug resistance by activating the vinculin/aryl hydrocarbon receptor (AhR)/ERK signaling pathway but also enhance susceptibility to breast cancer by upregulating the Esr1/HDAC6 pathway in female rats." (PMID 38341560, 2024). "Low Cry2 acetylation level showed a stronger inhibition of breast cancer cell growth, which inhibited by HDAC6, consistent with a previous report showing that high HDAC6 expression was associated with higher survival in breast cancer patients." (PMID 37024472, 2023). "Recently, the association between membrane−localized ER/HDAC6/α−tubulin has been demonstrated in ER−positive breast cancer cell lines." (PMID 36232636, 2022). "SMAR1 has been reported to regulate splicing of CD44 variants by deacetylation of Sam68 with help of HDAC6 in breast cancer cell lines." (PMID 33863392, 2021). "SMAR1 further inhibits metastasis via regulation of CD44 variants alternative splicing via HDAC6-mediated deacetylation of Sam68 in breast cancer cells." (PMID 33863392, 2021). "HDAC6, which is mostly cytoplasmatic, has been implicated in cancer and metastasis formation in breast cancer." (PMID 34944947, 2021). "Improved survival was shown to be associated with moderate to strong HDAC6 immunohistochemistry (IHC) expression in diffuse large B-cell, and breast cancer." (PMID 33322608, 2020). "Survival rates in breast cancer patients can be linked to the increased HDAC6 protein and mRNA expression." (PMID 31683808, 2019). "Similarly, in breast cancer patients, higher levels of HDAC6 are associated with smaller tumour size and low histological grade, in which the overexpression of HDAC6 is predominantly found in progesterone- and oestrogen-positive (ER+ve) tumours." (PMID 39941046, 2025). "The association of HDAC6 expression with the mentioned factors suggests that its expression is related to prognosis in bitches with simple mammary carcinomas and may be a useful antibody in the prognosis." (PMID 38028583, 2023). "These associations highlighted aberrant expression in mammary carcinomas compared to normal mammary tissues, indicating that epigenetic alterations exist in canine mammary neoplasms and that high HDAC6 expression may explain the observed hypoacetylation of H3 in neoplastic tissues." (PMID 40590021, 2025). "HDAC6 is closely associated with resistance to sorafenib and gefitinib in lung cancer cells, resistance to microtubule-targeting anticancer drugs in melanoma cells, tamoxifen resistance in breast cancer cells, and bortezomib resistance in multiple myeloma cells." (PMID 39063958, 2024). "The image on the left shows how HDAC6 inhibits the autophagy of breast cancer cells with damaged DNA." (PMID 40013196, 2025). "Hyperactivated ARID1A/phospho-HDAC6/FOXM1 forms similar condensates in Ewing’s sarcoma or breast cancer recruiting BAFs complexes, Pol II, and coactivators to remodel chromatin structure that drive oncogenic transcription and tumor progression." (PMID 40507965, 2025). "High expression of HDAC6 was found to promote protumor phenotypes in TAMs, and HDAC6 inhibition improved the response of breast cancer to ICB in part by stimulating an antitumor immune response." (PMID 40165290, 2025). "A recent study found induced HDAC6 activity in about 30% of breast cancer patients analyzed and suggested that HDAC6 deacetylates c-Myc to reduce its degradation, contributing to tumor cell viability." (PMID 40165290, 2025).
breast cancer (continued). "Epigenetic regulation of HDAC6 expression has been described in male breast cancer where the HDAC6 gene is significantly hypomethylated." (PMID 39941046, 2025). "Numerous studies have demonstrated that inhibition of HDAC6 activity exhibits promising anticancer efficacy in various tumours, including breast cancer and ovarian cancer." (PMID 39834092, 2025). "HDAC6 is overexpressed in several cancers such as breast cancer, pancreatic cancer, prostate cancer, ovarian cancer, myeloid leukemia, B and T cell lymphomas, glioblastoma, oral squamous cell carcinoma, bladder cancer, and lung cancer." (PMID 41300448, 2025). "In MCF-7 ER+ve breast cancer cells, oestrogen levels affected HDAC6 localisation in the nucleus, leading to the deacetylation of survivin." (PMID 39941046, 2025). "The development of an approach to predict breast cancer sensitivity to HDAC6 inhibition successfully stratified high- and low-HDAC6-score cancers based on sensitivity to HDAC6 inhibition." (PMID 39941046, 2025). "Previous studies revealed that HDAC6 inhibitors showed anti-metastatic effects in pancreatic and breast cancer cells in vitro and in vivo." (PMID 39063958, 2024). "HDAC6 has exhibited oncogenic properties across several cancer types, including endometrial cancer, breast cancer, and esophageal cancer." (PMID 38632516, 2024). "In CAFs of breast cancer, for example, HDAC6 is frequently up-regulated and promotes an immunosuppressive microenvironment." (PMID 38988323, 2024). "Elevated HDAC6 expression is positively correlated with cancer progression in oral squamous cell carcinoma, and estrogen stimulation increases HDAC6 gene expression in MCF-7 breast cancer cells." (PMID 39620228, 2024). "LAQ824 reduced the expression of ERα, PRβ, c-Myc, cyclin D1 and HDAC6 in breast cancer cells, leading to suppression of cellular proliferation." (PMID 36969235, 2023). "Breast cancer cells were incubated with different concentrations (1 nM to 100 μM) of free PI3‐Kδ/HDAC6, SAHA, IDL, and their encapsulated NPs (IDL‐NPs, SAHA‐NPs, and HSB‐510), to evaluate the relative cytotoxicities." (PMID 37693068, 2023). "In the present study, poloxamer L‐61 modified polylactic acid block copolymers were synthesized to prepare isoform‐specific single agent PI3‐Kδ/HDAC6 dual inhibitor encapsulated nanoformulation (HSB‐510) to treat breast cancer." (PMID 37693068, 2023). "In summary, we report a novel biodegradable polymeric nanoformulation of PI3‐Kδ/HDAC6 dual inhibitor (HSB‐510) based on PLA block copolymeric system for breast cancer therapy." (PMID 37693068, 2023). "MPT0G211, a HDAC6 inhibitor, exhibited an inhibition of tumor metastasis via attenuation of HDAC6 activity in breast cancer cells." (PMID 36969235, 2023). "The slow and steady release of the PI3‐Kδ/HDAC6 dual inhibitor from HSB‐510 led to 2–3 times higher in vitro IC50 values as compared to free PI3‐Kδ/HDAC6 dual inhibitor evaluated in breast cancer cell lines." (PMID 37693068, 2023). "Immunohistochemical expression of H3K9Ac, H4K12Ac, HDAC1, HDAC2 and HDAC6 in 61 samples of simple mammary carcinoma in female dogs." (PMID 38028583, 2023). "The present study aims to correlate the expression of H3K9Ac, H4K12Ac, HDAC1, HDAC2 and HDAC6 in simple mammary carcinomas in dogs with clinicopathological parameters and overall survival time." (PMID 38028583, 2023). "Histone deacetylase 6 (HDAC6) is reported to deacetylase cell microtubule structures, such as α-Tubulin and cortactin, and increase the formation of invadopodia that promotes breast cancer cell migration and invasion." (PMID 35216622, 2022). "Crucially, HDAC6 inhibitors have been shown to control breast cancer cell proliferation and migration both in vitro and in vivo." (PMID 34976203, 2022).
breast cancer (continued). "Individual HDACs have been reported to be overexpressed in tumors, such as HDAC1 in prostate, gastric, colon, and breast cancer, and HDAC6 in breast cancer, suggesting that aberrant expression of HDACs is largely related to cancer." (PMID 36505774, 2022). "In some cases, such as in breast cancer and glioblastoma, HDAC6 was shown to support tumour progression." (PMID 36330589, 2022). "HDAC6 was shown to decrease the expression of tumor suppressor mammalian STE20-like kinase 1 (MST1) by deacetylating MST1 in breast cancer cells." (PMID 36076996, 2022). "WT161, an HDAC6 inhibitor, can sensitize luminal breast cancer more effectively than other subtypes by activating the apoptotic protein X-Linked Inhibitor of Apoptosis (XIAP) and downregulating EGFR, HER2, and ERα." (PMID 35453496, 2022). "Ricolinostat is also a selective HDAC6 inhibitor that inhibits breast cancer migration and invasion." (PMID 35216622, 2022). "Recent studies indicate that invadopodia and invasion activities of breast cancer are controlled by HDAC6." (PMID 35163593, 2022). "The regulations of breast cancer cell invadopodia formation and invasion are through the HDAC6-dependent signaling pathway." (PMID 35163593, 2022). "Overexpressed HDAC6 has been connected with cell migration and invasion in breast cancer, especially in TNBC." (PMID 35163593, 2022). "HDAC6 inhibition is proved to upregulate E-cadherin, a marker of EMT, making breast cancer cells or peritoneal mesothelial cells less susceptible to undergoing EMT." (PMID 36457493, 2022). "A class II histone deacetylase mediates upregulated activation of STAT3 in breast cancer, histone deacetylase 6 (HDAC6), as well as prostaglandin E2 and COX2." (PMID 34488773, 2021). "HDAC6 inhibitors will be immensely valuable as adjuvants in the application of targeted cysteine-dependence therapy to treat various types of breast cancer." (PMID 34040090, 2021). "HDAC6 has a regulatory antitumor immune response in breast cancer and plays an atypical role in disseminated and invasive breast cancer." (PMID 34485153, 2021). "With respect to HDAC6, it is suggested that HDAC6 interacts with ERα in an ER ligand-dependent manner and subsequently upregulates deacetylation of α-tubulin in breast cancer cells." (PMID 32106418, 2020). "What is more, it showed that HDAC6 inhibition downregulated autophagy in differentiated breast cancer cells but upregulated autophagy in cancer stem-like cells." (PMID 33330506, 2020). "In breast cancer cell lines, carbamazepine inhibits HDAC6 activity, increases Hsp90 acetylation, induces HER2 protein degradation and upregulates p21 gene expression." (PMID 32365701, 2020). "For example, in human breast cancer, HDAC6 forms complexes with CDK1 and induces its P62-dependent autophagy degradation." (PMID 33330506, 2020). "HDAC6 is a cytoplasmic enzyme that is highly expressed in breast cancer, advanced primary acute myeloid leukemia (AML), primary oral squamous, and laryngeal squamous cell carcinoma." (PMID 33322608, 2020). "Consistent with this notion, recent data have emphasized a relevant role for the GRK2/HDAC6 axis in breast cancer." (PMID 31432234, 2019). "HDAC6 is highly expressed in breast cancer, is used as a late-stage cancer indicator, and is present in both the positive progesterone and α-estrogen receptors." (PMID 31683808, 2019). "In this study, we examined the role of HDAC6 in breast cancer pathogenesis using HDAC6 knockdown and HDAC6-selective inhibitor WT161, in breast cancer cell lines." (PMID 29113288, 2017). "In this report, we determine that both chemotherapeutic agents and proteolytic stress induce CDK1 degradation in human breast cancer MCF7 cells through p62/HDAC6-mediated selective autophagy." (PMID 28855742, 2017). "A balance of acetylation and deaceylation by ATAT1/HDAC6 enzymes regulates breast cancer cell migration and invasion." (PMID 27902487, 2017).